INS (insulin)
Diseases named in the same sentence as INS in open-access papers (continued):
Sharing a sentence is not in itself a finding about the gene and the disease.
Hyperglycemia (continued). "Since there is hyperglycemia in the fasting and fed states in SCD mice compared with sex-matched WT and SCT mice at this young age, it would be expected that serum insulin levels should be greater in SCD mice." (PMID 40294908, 2025). "Transgenerational mice studies revealed that F1‒F3 male progeny from prenatal AE lineage develop hyperglycemia and glucose intolerance with advanced age and HFD, primarily due to defective insulin secretion." (PMID 39934105, 2025). "While insulin-independent pathways such as GLUT1 and sodium/glucose cotransporter 1 (SGLT1) allow a stable influx of glucose into cardiomyocytes, hyperglycaemia results in the accumulation of glucose and glycolysis intermediates in the cytosol." (PMID 40243689, 2025). "Concurrently, diacylglycerol accumulation inhibits insulin signaling through PKC translocation, exacerbating hyperglycemia and ceramide synthesis; ceramides, in turn, activate NLRP3 inflammasome, amplifying inflammation and fibrosis." (PMID 41262444, 2025). "Advances in sustained-release insulin pumps, genetically engineered long-acting insulin, and the anti-CD3 monoclonal antibody teplizumab have improved hyperglycemia management in T1D patients." (PMID 41012130, 2025). "Once chronic hyperglycemia is corrected, GIP-mediated insulin secretion is restored, allowing tirzepatide to enhance insulin secretion through both the GIP and GLP-1 receptors." (PMID 40607140, 2025). "In addition, long-term hyperglycemia (glucotoxicity) and hyperlipidemia (lipotoxicity) synergistically amplify inflammatory responses, accelerate the functional failure of β cells, and ultimately lead to the inability of insulin secretion to compensate for IR, thereby triggering T2DM." (PMID 41044789, 2025). "In addition, PYY may also improve islet secretory function post-MBS, and GLP-1 is known to increase glucose-dependent insulin secretion and suppress glucagon during hyperglycemia, all factors that likely contribute to the metabolic improvements seen in participants of IMPROVE-T2D." (PMID 39911520, 2025). "In rodent models, central IL-1β and IL-6 suppress hypothalamic insulin sensitivity and disrupt GABA/glutamate balance, amplifying hyperglycemia and appetite dysregulation." (PMID 40869170, 2025). "These pathways disrupt insulin signaling via mechanisms such as promoting serine phosphorylation of IRS, ultimately resulting in IR, hyperglycemia, and exacerbation of T2DM." (PMID 41044789, 2025). "However, in the absence of significant hyperglycemia, insulin therapy alone may cause profound hypoglycemia." (PMID 40941597, 2025). "After 60 min of a single dose of 10 μg/kg, the procyanidins activated insulin and AMPK signaling pathways to induce GLUT4 translocation in muscle and suppress acute hyperglycemia in mice." (PMID 39795230, 2025). "IAS pathogenesis involves the formation of insulin-IAA complexes, inducing first a mild hyperglycemia in the postprandial period, followed by hypoglycemia." (PMID 40696585, 2025). "Participants who did not complete the follow-up questionnaire at month 12 (n=1079) were predominantly male, younger, had higher levels of hyperglycaemia, and most used MDI as their insulin treatment." (PMID 40924111, 2025). "Another study reported that chronic hyperglycemia, mimicking T2D, induced the GLP-1R to switch from Gαs to Gαq as the proximal step leading to increased insulin secretion." (PMID 40526441, 2025). "This reflects a known pathophysiological difference: relative insulin resistance and a higher glycemic set point in GCK-hyperglycemia patients." (PMID 41409604, 2025). "Moreover, other rat studies have shown that some honey phenols, such as quercetin, could alleviate hyperglycemia by stimulating insulin signaling and GLUT-4 expression through increasing the tyrosine phosphorylation on insulin receptor substrate (IR), and direct activation of the P13k/Akt pathway." (PMID 40901285, 2025).
Hyperglycemia (continued). "However, after STZ treatment, the percentage of insulin-positive cells in both groups were similar, suggesting that Glut4 activation in the muscle may have helped mitigate severe DM symptoms by enhancing glucose uptake and reducing hyperglycemia." (PMID 40556865, 2025). "If the glycemic control of the diabetic pregnant woman is deficient in the first weeks of gestation when the process of somitogenesis takes place, and the fetal pancreas does not yet release insulin, fetal hyperglycemia could, theoretically, be the cause that leads to the development of CRS." (PMID 40004100, 2025). "Consistent with hyperglycemia, we found Ins1 to be downregulated in the pancreas from MKP-2 KO mice, suggesting a role for MKP-2 in the regulation of insulin secretion." (PMID 39996734, 2025). "We found that in vivo administration of SPARC significantly ameliorated hyperglycemia, gradually restored STZ-induced islet damage, and facilitated the recovery of β-cells function and insulin production." (PMID 41185072, 2025). "PSP improve insulin sensitivity, reduce glycated serum protein levels, and normalize lipid metabolism in T2DM mice, directly alleviating hyperglycemia and dyslipidemia." (PMID 40959703, 2025). "Under insulin-resistant conditions, impaired insulin signaling reduces GLUT2 transport activity, diminishing glucose uptake in these tissues and contributing to hyperglycemia." (PMID 41471379, 2025). "This suggests that chronic hyperglycemia during gestation leads to downregulation of INSR, thus diminishing its signaling capacity and contributing to impaired insulin-mediated vascular responses." (PMID 41373661, 2025). "During postprandial hyperglycemia, GLUT-2 facilitates continuous glucose uptake, triggering insulin secretion to maintain glucose homeostasis." (PMID 40429763, 2025). "Furthermore, hyperglycemia may trigger the generation of free radicals, resulting in DNA damage in addition to excessive production of nitric oxide, which functions as an inflammatory mediator that harms β-cells and reduces insulin synthesis." (PMID 39846548, 2025). "Based on the traditional insulin pumps, the new insulin pump (sensor augmented pump [SAP]) incorporates CGM, hyperglycemia, and hypoglycemia threshold alarms and trend prediction capabilities." (PMID 41180388, 2025). "In contrast, our geriatric, leaner Indian cohort likely exhibits impaired insulin secretion (low HOMA-B), limiting hepatic IGF-1 production despite hyperglycemia." (PMID 41393761, 2025). "Among these, so-called “resistant” β-cells maintain high INS, MAFA, and PDX1 expression under diabetic conditions, preserving function despite hyperglycemia and inflammation." (PMID 41584842, 2025). "This study provides valuable insights into the effects of hyperglycemia on VEGF-A and AGT expression in two physiologically relevant retinal cell types and highlights the differential impacts of various insulin analogues." (PMID 40510890, 2025). "Hyperglycemia promotes NOX activation, worsening OS, which can lead to abnormal insulin secretion and disrupted lipid metabolism." (PMID 40599237, 2025). "All studies comparing the sliding scale insulin (SSI) regimen with other regimens have shown the inferiority and ineffectiveness of the sliding scale in controlling hyperglycemia." (PMID 39939862, 2025). "Alternatively, stress hyperglycemia in acute pancreatitis triggers a cascade of neuroendocrine and inflammatory responses that sharply elevate glucose levels and can precipitate DKA in insulin-intolerant individuals." (PMID 40710886, 2025). "Stress hyperglycemia and inflammation have some common pathogenic mechanisms since both are related with cytokines’ release, such as tumor necrosis factor-α (TNF-α), which might promote gluconeogenesis by stimulating glucagon production, as well as inhibit post-receptor insulin signaling." (PMID 39860413, 2025).
Hyperglycemia (continued). "Next, we tested their glucose tolerance, insulin tolerance, and glucose-stimulated insulin secretion (GSIS) prior to when the βOGT-KO mice developed hyperglycemia and reduced body weight." (PMID 39388284, 2024). "Insulin treatment is essential for people with T1DM, not only to limit hyperglycaemia but also to avoid other severe metabolic disturbances such as hypertriglyceridemia and diabetic ketoacidosis (DKA)." (PMID 38542818, 2024). "After regular insulin injections, adequate hydration, and CVVH treatment during hospitalization, the patient's hyperglycemia with diabetic ketoacidosis subsided, and his renal function gradually improved." (PMID 38799756, 2024). "The hyperglycemia observed in the IFG state and IGT state implicates a bi-hormonal effect in which glucagon raises the hepatic glucose output, and insulin diminishes the peripheral utilization of glucose." (PMID 38665134, 2024). "Hyperglycemia commonly occurs in patients after intense EXE, particularly if insulin concentrations are reduced." (PMID 38542818, 2024). "Hyperglycemia and HTG in heterozygous hamsters were reversed to pre‐diabetic levels following intraperitoneal insulin administration." (PMID 39529532, 2024). "Silibinin prevented the decrease in insulin due to STZ, exhibited a hyperglycemia‐reducing effect and decreased the elevation of ALT." (PMID 38726421, 2024). "It has been reported that elevated fructosamine levels indicate prolonged hyperglycemia, while the OGTT provides insights into insulin sensitivity and resistance." (PMID 39203819, 2024). "Particularly, it has been shown that AGEs can contribute to the induction of oxidative stress, leading to a decrease in insulin secretion and GLUT4 translocation, an increase in blood glucose levels, and hyperglycemia development." (PMID 39062550, 2024). "In our study, when bolus insulin was required to manage postprandial hyperglycemia, we opted to add NPH insulin (either as NPH or as a 70/30 NPH/regular insulin mix) or porcine lente insulin once or twice daily to the treatment protocol." (PMID 38831362, 2024). "BPA-exposed mice exhibited elevated HOMA-IR, indicating reduced insulin sensitivity, while lower HOMA-β scores suggested β-cell damage, revealing the strain on pancreatic cells combating hyperglycemia due to BPA exposure." (PMID 38580733, 2024). "Currently, metformin is widely utilized as the first-line medical treatment for T2DM individuals, as it ameliorates hyperglycemia, but it is used less commonly in T1DM individuals due to the requirement for insulin supplementation." (PMID 39125657, 2024). "All the subjects in this study were undergoing medication for hyperglycemia ranging from oral hypoglycaemic agents (OHA) (n=79; 66.4%), insulin (n=8; 6.7%), and OHA with insulin (n=32; 26.8%)." (PMID 39224717, 2024). "For example, hyperglycemia/hyperlipidemia-induced oxidative stress and inflammation may activate platelets either directly or by impairing NO bioavailability while at the same time insulin can exert mild antiplatelet effects, at least in insulin sensitive subjects." (PMID 38255980, 2024). "All the subjects in this study were undergoing medication for hyperglycemia ranging from OHA, insulin, and both OHA with insulin." (PMID 39224717, 2024). "Diabetic ketoacidosis (DKA) is a life-threatening medical emergency and is a direct result of a lack of insulin or insulin resistance, which leads to increased levels of counterregulatory hormones, such as glucagon, cortisol, and catecholamines, thereby causing hyperglycemia." (PMID 39360087, 2024). "In vivo, HM-chromanone can reduce hyperglycemia and ameliorate dyslipidemia in C57BL/Ksj-db/db mice, the effect of 30 mg/kg HM-chromanone for 6 weeks on levels of HbA1c, plasma insulin, HOMA-IR and serum lipid significantly normalized." (PMID 38799166, 2024).
Hyperglycemia (continued). "Concomitant with increasing glucagon levels, serum insulin concentrations peaked approximately 2 h post-infusion in the CRI-HI group, an appropriate response to hyperglycemia that explains the normalization of glucose concentrations." (PMID 38814331, 2024). "Hyperglycemia in patients with MODY1 and MODY3 tends to increase over time, resulting in the need for treatment with oral hypoglycemic agents or insulin." (PMID 39902162, 2024). "During the immediate post-operative period, she had hyperglycaemia consistent with PTDM and was started on insulin." (PMID 38290219, 2024). "Additionally, CKD is associated with reduced insulin secretion and sensitivity, elevated adipokine levels such as leptin, and other CKD-related issues such as hyperparathyroidism and an inflammatory state, which contribute to an increased risk of hyperglycemia." (PMID 39439522, 2024). "In vitro experiments and in vivo pharmacologic experiments provided evidence that under hyperglycemia, OXTR activation can potentiate insulin secretion and glucose suppression." (PMID 39764245, 2024). "This study aimed to assess the impact of maternal hyperglycemia severity, classified as GDM-G1 (diet treatment) and GDM-G2 (insulin treatment) on colostral appetite-regulating molecules." (PMID 38612666, 2024). "Secretion of AVP and activation of AVP receptors are regulated by changes in blood pressure and body fluid osmolality, hypoxia, hyperglycemia, oxidative stress, inflammation, and several metabolic hormones; moreover, AVP turnover is regulated by insulin." (PMID 39769071, 2024). "It is believed that GLP-1 analogues effectively slow down gastric emptying, small intestinal transit, decrease postprandial hyperglycaemia, and regulate endogenous GLP-1 excursions, and incretin-stimulated insulin secretion." (PMID 38370356, 2024). "Elevated levels of serum glucose can trigger INS and ADPN release or decrease glucagon production to alleviate stress from hyperglycemia and maintain the glucose balance." (PMID 38668364, 2024). "Glucose-stimulated insulin secretion (GSIS) of pancreatic beta cells plays a key role in maintaining glucose homeostasis and preventing hyperglycemia." (PMID 39296548, 2024). "This could in part relate to the pitfalls of testing for gestational diabetes in pregnancy and perhaps highlights the fact that complications of reduced insulin sensitivity e.g. fetal macrosomia persist in “at risk” women even in the absence of maternal hyperglycaemia." (PMID 38225599, 2024). "Metformin, insulin sensitizing drug, potentiated the therapeutic efficacy of hASCs in HFD-diabetic mice as shown by enhanced reversal of hyperglycemia, hyperinsulinemia and triglyceridemia." (PMID 39468609, 2024). "PRLRs in pancreatic β cells improve insulin release in response to blood glucose at physiological PRL level, though hyperprolactinaemia can induce hyperglycaemia and IR." (PMID 39663784, 2024). "Several studies haveconcluded that bariatric surgery is superior to pharmacotherapyfor the control of hyperglycemia inT2DM, with its ability to increase endocrine and glucagon-like peptide-1 (GLP-1), reduce HI, andimprove insulin sensitivity." (PMID 38699692, 2024). "In the recommendations of the most recent consensus statements for managing hyperglycemia in T2DM, the use of insulin is primarily reserved for individuals in whom other therapeutic strategies have failed." (PMID 38559691, 2024). "Additionally, it has been suggested that intensive insulin therapy in the first weeks or months after the diagnosis of severe hyperglycemia could, in addition to improving hyperglycemia, reverse damage caused by glucotoxicity and reduce the metabolic memory footprint." (PMID 38559691, 2024). "Compared to insulin monotherapy, patients with T1DM who received amylin analog in addition to insulin experienced a greater reduction in pre-prandial hyperglycemia and a corresponding decrease in glucagon levels." (PMID 39493778, 2024).
Hyperglycemia (continued). "By breaking down incretin peptides including glucagon-like peptide 1 (GLP-1) and glucose-dependent insulinotropic polypeptide, which stimulate the release of insulin from pancreatic β cells, DPP4 plays a crucial role in regulating postprandial hyperglycemia." (PMID 38337597, 2024). "Compared to fasting state, insulin and GLP-1 secretion in presence of local postprandial hyperglycaemia suppresses glucagon release." (PMID 38579770, 2024). "Moreover, many patients face challenges with proper insulin storage, as refrigeration is often unavailable, and if available, frequent power outages prevent proper storage, this results in challenges in control of hyperglycemia which in turn leads to diabetic retinopathy in our setting." (PMID 40027085, 2024). "Rebound hyperglycemia as DKA resolves is common in the pediatric population and is reduced by 19% with early administration of insulin glargine." (PMID 39136541, 2024). "The induced beta cells can ameliorate hyperglycemia induced by STZ by inducing local vasculature remodeling and secreting insulin." (PMID 38844555, 2024). "It prevented the decrease in insulin due to STZ, exhibited a hyperglycemia‐reducing effect, and decreased the elevation of ALT." (PMID 38726421, 2024). "Current research reveals how hyperglycemia is potentiating the viral entry of SARS-CoV-2 into pancreatic β-cells, resulting in their dysfunction and inability to produce insulin." (PMID 39205219, 2024). "Furthermore, the abilities of both Ad-MSCs to control hyperglycemia in diabetic rats in vivo was assessed through measuring fasting blood glucose (FBGs), body weight (BW), histopathological examination of both pancreas and liver and immunoexpression of insulin in pancreata of study groups." (PMID 38698488, 2024). "Immediately post-transplant, random blood glucose (BG) measurements above 200 mg/dL or insulin requirement are defined as early in-hospital post-transplant hyperglycemia (EPTH), and this requires insulin treatment and close monitoring." (PMID 39451871, 2024). "On one hand, in vitro experiments and in vivo pharmacologic experiments provided evidence that under hyperglycemia, OXTR activation can potentiate insulin secretion and glucose suppression." (PMID 39764245, 2024). "Previous findings have shown that insulin use was more common in the CGM group than in the SMBG group, which demonstrated the advantages of CGM in the accurate detection of hyperglycemia and hypoglycemia." (PMID 37152928, 2023). "There has been a growing interest in using HIIE following meals as a time-efficient approach to counter postprandial hyperglycemia, as HIIE has been shown to enhance glucose tolerance and insulin sensitivity." (PMID 37892564, 2023). "To generalize these findings, we used a model of hyperglycaemia induced by the administration of streptozotocin (STZ), which leads to rapid destruction of pancreatic insulin-producing β cells, driving acute hyperglycaemia." (PMID 38093014, 2023). "Although the mice fed HAMSB also developed hyperglycemia, these mice had decreased HOMA-IR, indicating improved insulin sensitivity compared to the control mice." (PMID 36901964, 2023). "Milk-derived whey ameliorated insulin secretion in obese, prediabetic, and T2DM subjects, reducing postprandial hyperglycemia and improving lipidemia by exerting antioxidative effects, as an enhancer of GSH synthesis and endogenous antioxidative enzyme system." (PMID 37372041, 2023). "Over time, β-cell malfunction could be further accentuated by the progressive hyperglycemia, since it has been shown that chronic exposure to high glucose levels causes ER stress and hyperactivation of both IRE1 and ATF5, leading to the suppression of insulin gene." (PMID 36835101, 2023). "Relative to LFD mice, fasting blood glucose and serum insulin levels were 47% and 453% higher, respectively, in HFD mice, showing that HFD induced mild hyperglycemia and severe hyperinsulinemia in OVX mice." (PMID 37935669, 2023).